INS (insulin)
Diseases named in the same sentence as INS in open-access papers (continued):
Sharing a sentence is not in itself a finding about the gene and the disease.
diabetes (continued). "Compared to other treatment groups, there was a higher prevalence of diabetes in the ACEI (48.7%) and ARB initiators (37.1%); with a corresponding pattern observed in non‐insulin antidiabetic drug usage." (PMID 41582443, 2026). "Type of diabetes medications was a significant factor, with patients using both OHA and insulin reporting significantly lower convenience score compared to those using OHA only (β = − 7.275, 95% CI [− 10.41, − 4.142], p < 0.001)." (PMID 41311517, 2026). "Completers had similar diabetes duration (15 [IQR 5, 21] vs 14[IQR 5, 20] years, P = .51) and 61% vs 69% were on insulin prior to admission (P = .37)." (PMID 41376653, 2026). "In our previous studies, over 50% of adults with newly diagnosed type 2 diabetes mellitus (mean HbA1c 9.7%–10%) obtained 1‐year remission after SIIT, accompanied by improvement in β‐cell function and insulin sensitivity." (PMID 41521023, 2026). "After adjusting for HbA1c, BMI, and diabetes duration through ANCOVA, patients on insulin therapy presented significantly higher NOX2 levels (22.8 ± 1.5 ng/mL) compared to those on metformin or DPP-4 inhibitors alone (p = 0.041 and p = 0.028, respectively)." (PMID 41607455, 2026). "It positively affects diabetes by inhibiting dipeptidyl peptidase-4 (DPP-4), α-glucosidase, and α-amylase, while simultaneously increasing pancreatic insulin secretion and improving insulin sensitivity in organs." (PMID 41641144, 2026). "In conclusion, diabetes led to a reduction in the full-length, functional NEP protein in urine and increased its fragmentation, both of which were reversed by insulin therapy, indicating NEP stabilization." (PMID 41601953, 2026). "In patients with type 1 diabetes mellitus in the DK/DKA group, hyperglucagonemia was correlated with a decrease in insulin secretion relative to hyperglycemia." (PMID 41292690, 2026). "Among dietary strategies, carbohydrate counting stands out as the cornerstone of nutritional management in type 1 diabetes mellitus (T1DM), as it enables the adjustment of insulin doses." (PMID 41564321, 2026). "The median duration of diabetes was 21 years (IQR: 12; 32); 1747 (92%) patients used continuous glucose monitoring (CGM), mainly flash monitoring and 56% used insulin pumps." (PMID 41328549, 2026). "In conclusion, we found that adults with diabetes and pre‐existing SMI in Scotland are prescribed each of metformin and insulin sooner after the diagnosis of diabetes than adults with type 2 diabetes only." (PMID 41235789, 2026). "Clinical studies and meta-analyses show that ginger supplementation improves insulin sensitivity, enhances insulin secretion, and lowers fasting blood glucose (FBG) and HbA1c in patients with type 2 diabetes mellitus." (PMID 41599361, 2026). "Comparing bolus insulin prescription patterns, fCGM users were prescribed ultrashort-acting analogs more frequently than those who perform BGM for all types of diabetes, except GDM." (PMID 39901274, 2025). "Encompassing 90–95% of all global diabetes cases, T2DM is characterized by the impaired secretion of insulin from beta cells in the pancreas, along with reduced insulin sensitivity in peripheral tissues, such as skeletal muscle, liver, and adipose tissue." (PMID 41373570, 2025). "These compounds, such as resveratrol, curcumin, and quercetin, have demonstrated beneficial effects on insulin signaling, AGE–RAGE signaling, and efficient glycemic control, making phenolics valuable adjuncts to conventional diabetes treatments." (PMID 41150789, 2025). "For instance, Aguirre’s team cultured self-assembling hCOs in a differentiation medium that simulates pregestational diabetes (PGD) and contains high insulin and glucose to investigate the effects of PGD on cardiac development." (PMID 41511291, 2025). "In diabetes, TNF-α interferes with insulin signaling pathways, leading to insulin resistance and elevated blood glucose levels." (PMID 40283848, 2025).
diabetes (continued). "Thirty-six percent of the participants educated by the diabetes educators demonstrated an appropriate IIT, such as storage, priming the insulin pen (54%), skin folding (63%), injection hold time, and “use-by” date." (PMID 40376558, 2025). "Subgroup analyses were performed according to age, sex, BMI, diabetes status, renal disease, SOFA score, and insulin use, with strict adjustment for other potential confounders." (PMID 40190402, 2025). "Diabetes mellitus (DM) is a prevalent endocrine disorder characterized by a complex syndrome of metabolic dysregulation, primarily manifested as hyperglycemia owing to inadequate insulin secretion or impaired insulin action." (PMID 40093018, 2025). "Among a population of liver-transplanted individuals with diabetes, we evaluated 68 patients before, 6, 12 and 18 months after starting a GLP1RA-based therapy, as add on to metformin or insulin." (PMID 40496570, 2025). "Type 2 diabetes mellitus (T2DM) is a group of metabolic diseases characterized by chronic hyperglycemia, whose core mechanisms involve insufficient insulin secretion and insulin resistance." (PMID 41488105, 2025). "Diabetes mellitus, a chronic metabolic disease characterized by insufficient insulin secretion and/or insulin resistance (GBD, 2021 Diabetes Collaborators, 2023), is an intractable global public health problem." (PMID 40308758, 2025). "Type 1 diabetes mellitus (T1DM) is characterized by an autoimmune response that targets and destroys insulin-producing pancreatic beta cells, resulting in insufficient insulin production." (PMID 40002691, 2025). "Second, low/middle SDI regions face healthcare constraints (e.g., limited insulin access and screening programs), exacerbating SHS-driven diabetes through delayed detection/intervention." (PMID 40365229, 2025). "Insulin normally activates glycogen synthase through dephosphorylation, but in PDAC patients with diabetes, there is an abnormal skeletal muscle response to insulin stimulation." (PMID 40507369, 2025). "Their mechanisms of action, including insulin-mimetic effects, stimulation of β-cell regeneration, and reduction in oxidative stress, highlight their clinical relevance and support the idea that these species could be considered as adjuncts in diabetes management." (PMID 40732323, 2025). "We also could not stratify the severity of diabetes by insulin use for risk adjustment." (PMID 40526615, 2025). "Recipients included more females (56%) with a median duration of diabetes at first ITx of 31 years (IQR 23, 41) and insulin requirements of 0.50 units/kg/day (IQR 0.50, 0.70) prior to transplant." (PMID 40729316, 2025). "Maternal serum levels of NLR, PLR, MLR, SIRI, AISI, and MPV were significantly elevated in the pregestational diabetes, whereas CAR, FAR, and fibrinogen were predominantly increased in the insulin-treated gestational diabetes." (PMID 41227015, 2025). "Furthermore, improvements in brain insulin sensitivity, which influence appetite regulation and energy fluxes, have been observed when physical activity is paired with a low-fat diet, potentially benefiting mental and cognitive function in individuals with diabetes." (PMID 41141270, 2025). "Its deletion triggers ROS-driven beta cell death and diabetes, whereas overexpression enhances NRF2-dependent antioxidant defense but suppresses insulin secretion." (PMID 41373704, 2025). "Type 2 diabetes mellitus (T2DM), which makes up more than 90% of all cases of diabetes, is characterized by decreased insulin sensitivity and relative insulin insufficiency." (PMID 41146776, 2025). "Diabetes mellitus (DM) is a metabolic disorder characterized by chronic hyperglycemia due to either autoimmune destruction of insulin-producing β-cells (Type 1 DM), insulin resistance (Type 2 DM), or glucose intolerance occurring during pregnancy (gestational DM)." (PMID 40142159, 2025).
diabetes (continued). "The chronic metabolic disease known as diabetes mellitus, and more specifically type 2 diabetes (T2DM), is typified by hyperglycemia, insulin resistance, and decreased insulin secretion." (PMID 41170369, 2025). "A possible explanation is that in diabetes animal models, HDL-C and Apo A1 improve insulin sensitivity and pancreatic β-cell survival and function, which in turn improves glycemic control." (PMID 40142241, 2025). "As IDE is the principal protease responsible for insulin degradation in vivo, ML345 and its derivatives are considered to enhance insulin signaling and hold promise for the treatment of diabetes." (PMID 41231359, 2025). "Metformin was prescribed to 85.5% of the uncontrolled diabetes group, followedby sodium-glucose co-transporter 2 inhibitors (SGLT-2i) (53.9%) and insulin(48.7%)." (PMID 40630464, 2025). "Collectively, these findings establish lupanine as a glucose-sensing insulin secretagogue and modulator of β-cell excitability, representing a promising alkaloid for managing type 2 diabetes mellitus through KATP channel regulation and insulin gene activation." (PMID 41515341, 2025). "For high risk MASH (FAST score ≥0.35), the intersection of features identified by both the Boruta and lasso methods yielded a refined set of six features for the subsequent model construction: age, diabetes, ALT, AST, insulin treatment, and TyG-BMI index." (PMID 41341688, 2025). "Type 2 diabetes mellitus (T2DM) is a chronic metabolic disorder characterized by insulin insensitivity as a result of insulin resistance, decreased insulin production, and ultimately pancreatic beta‐cell insufficiency." (PMID 40309648, 2025). "Importantly, as a clinical medicine for the treatment of diabetic peripheral neuropathy, clinical trials suggested that lipoic acid could reduce peripheral neuropathy pain intensity experienced by patients with type 2 diabetes mellitus and improve insulin sensitivity in prediabetic individuals." (PMID 41066195, 2025). "For ALR, we observed a significant inverse correlation with cardiometabolic biomarkers (WHR, TG, insulin, AIP, and VAI) in the obesity and diabetes groups; however, ALR was positively correlated to HDL." (PMID 40095937, 2025). "These extracts may function through various mechanisms, such as enhancing insulin sensitivity, improving glucose uptake in peripheral tissues, modulating pancreatic β-cell function, and exerting antioxidant and anti-inflammatory effects, all of which are beneficial in diabetes management." (PMID 40563946, 2025). "Their role is crucial in diabetes mellitus (DM), since their dysfunction drives β-cell apoptosis, immune activation, and chronic inflammation through excessive ROS production, worsening endogenous insulin secretion." (PMID 40507468, 2025). "Type 2 diabetes mellitus (T2DM) is a chronic metabolic disorder characterized by progressive β-cell dysfunction and peripheral insulin resistance, leading to dysregulated glucose homeostasis and sustained low-grade inflammation." (PMID 41306436, 2025). "A 12 week intervention in overweight/obese patients with diabetes showed reductions in fasting plasma glucose (FPG), insulin injection dose, and HOMA-IR, and compared with the DASH diet, the legum-based DASH diet reduced FPG and HOMA-IR more significantly." (PMID 41229546, 2025). "This study demonstrates that in the process of diabetes induced by a high-fat diet, the expression of the upstream PI3K in the insulin upstream signaling pathway, PI3K/Akt, decreases with the prolonged duration of high-fat diet." (PMID 39761309, 2025). "Animal models of streptozotocin-induced diabetes further validate these mechanisms, showing significant reductions in fasting blood glucose (FBG) and improved insulin sensitivity upon M. charantia extract administration." (PMID 40283911, 2025).
diabetes (continued). "In this microsimulation study, Sanjay Basu and colleagues assess the potential impact of newer diabetes medications, such asGLP-1 receptor agonists and SGLT2 inhibitors, on insulin dosage and health outcomes in low- and middle-income countries." (PMID 40245017, 2025). "Oral medications serve as the cornerstone for treating T2DM, whereas injectable options, including insulin and glucagon-like peptide-1 receptor agonists (GLP-1 RAs), are implemented for both type 1 diabetes mellitus (T1DM) and more advanced stages of T2DM." (PMID 40648562, 2025). "For instance, The Environmental Determinants of Diabetes in the Young (TEDDY) study has identified that GAD AAb arise first in children with HLA-DR3/3 haplotypes, while insulin-only AAb were more prevalent in HLA-DR4/8 patients." (PMID 41480350, 2025). "A decrease in the levels of PEDF that are found in circulation has the potential to improve insulin sensitivity, which would position PEDF as a possible novel therapeutic target for diabetes mellitus and other metabolic disorders, respectively." (PMID 40141412, 2025). "The diabetes markers and lipid profile findings are as follows: The core group exhibited significant reductions in plasma FBG, PBG, HbA1c, insulin levels, and the HOMA-IR index, alongside notable increases in iron and HDL-C levels." (PMID 40428900, 2025). "The risks of hypoglycemia are greater in people with diabetes and CKD especially if people are on insulin treatment, sulfonylurea or glinides." (PMID 41141497, 2025). "Background/Objectives: Type 2 diabetes mellitus (T2DM) is a complex metabolic disorder characterized by insulin resistance, impaired insulin secretion, and chronic hyperglycemia." (PMID 41295241, 2025). "The previously published study using this cohort demonstrated a robust improvement in insulin‐stimulated glucose uptake after HIIT in both groups, with similar increases in muscle glucose clearance in the trained legs of the diabetes and control groups." (PMID 40413649, 2025). "Type 1 diabetes mellitus (T1DM) involves the destruction of pancreatic β-cells, requiring ongoing insulin therapy." (PMID 40428118, 2025). "Furthermore, 87.5% were aware that patients with diabetes need to carry an identity document (ID) indicating their condition while traveling abroad, and 84.1% knew that patients with diabetes traveling to the East region may need to increase their insulin dose." (PMID 40901237, 2025). "In diabetes, MGO is formed in high levels within endothelial cells as a result of insulin-independent uptake of glucose, resulting in increased glycolysis." (PMID 39414727, 2025). "The Diabetes Control and Complications Trials (DCCT) showed that intensive insulin treatment in type 1 diabetes reduced HbA1c by 2% (from 9% to 7%) over 6.5 years and lowered neuropathy incidence by 60%." (PMID 41280964, 2025). "This study underscores the critical role of miR-4428 and miR-185-5p in Type 2 Diabetes Mellitus (T2DM), particularly in insulin sensitivity and glucose homeostasis." (PMID 40282289, 2025). "Among patients with diabetes inadequately controlled by metformin, SGLT2 inhibition reduced circulating biomarkers of inflammation and fibrosis compared to treatment with the insulin secretagogue glimepiride in 1–2 years follow up." (PMID 39950157, 2025). "Type 2 diabetes mellitus (T2DM) is a chronic metabolic disorder characterized by insulin resistance and impaired insulin secretion, leading to persistent hyperglycemia." (PMID 40918786, 2025). "The most commonly used concomitant anti-diabetes agents were biguanides and SGLT2 inhibitors while insulin was used in an approximately quarter of participants." (PMID 41040428, 2025). "The current analysis reports the additional impact of diabetes in PCI patients with polyvascular disease, which was primarily driven by patients who were insulin-treated." (PMID 40687396, 2025).
diabetes (continued). "Type 2 diabetes mellitus (T2DM) is a heterogeneous metabolic condition characterized by hyperglycemia, insulin resistance, and impaired insulin secretion." (PMID 40161188, 2025). "Specifically, in type 2 diabetes mellitus (T2DM), PXR influences disease progression by regulating glucose metabolism and insulin sensitivity." (PMID 40869350, 2025). "They exhibited lower prevalence of diabetes and sepsis, lower usage rate of amiodarone, heparin, beta blocker, CCB and insulin." (PMID 40640797, 2025). "This substitution, replacing a polar amino acid with a non-polar one, was predicted to impair the inhibitory activity of PAX4 on the INS and GCG promoters, leading to hyperglycemia and diabetes." (PMID 41153735, 2025). "For persons with diabetes (PWD) with high total daily insulin requirements (TDI), one potential barrier is the limited capacity of insulin cartridges, which can hold between 1.6-3.0 mL or the equivalent of 160–300 units of U100 insulin (U100)." (PMID 41230085, 2025). "In rats with diabetes induced by the administration of STZ and nicotinamide (NA), blood insulin concentrations were indeed raised." (PMID 40806520, 2025). "The DM group experienced the process of diabetes modeling; the islet β cells were destroyed by STZ, and the insulin level was reduced." (PMID 39877628, 2025). "Concerning the different types of diabetes, for those with T1DM, T2DM and GDM, fCGM users were prescribed basal and bolus insulin more often than those who perform BGM, while for LADA there was not a significant difference." (PMID 39901274, 2025). "Another critical area for future research is the interaction between adjunctive therapies and advanced diabetes technologies such as CGM and closed‐loop insulin delivery systems." (PMID 40130476, 2025). "Diabetes mellitus type 2 (T2DM) is characteristically a metabolic disease, chronic in nature, marked by reduced insulin sensitivity and progressive decline in insulin production, resulting in persistently high blood glucose levels." (PMID 41246652, 2025). "Total daily dose of insulin degludec/aspart (IDegAsp) by regimen in individuals with type 1 (T1DM) and type 2 diabetes mellitus (T2DM)." (PMID 41293743, 2025). "Prostaglandin E2 (PGE2) is an endogenous inhibitor of glucose-stimulated insulin secretion (GSIS) and plays an important role in pancreatic β-cell dysfunction in type 2 diabetes mellitus (T2DM)." (PMID 40028769, 2025). "In the present study, the control group exhibited a mean TTR of 0.43, whereas significantly lower values were observed in the diabetes subgroups: 0.40 in diet-regulated GDM, 0.34 in insulin-treated GDM, and 0.29 in PGDM." (PMID 41227015, 2025). "Also, inhibiting chemerin’s receptor, ChemR23, with a small molecule, CCX832, might diminish the downstream inflammatory effect, reduce oxidative stress, and worsen insulin signaling in diabetes, suggesting it could be targeted to improve cardiovascular health in metabolic diseases." (PMID 40564199, 2025). "The mean HbA1c concentration was 7.0 ± 1.5 %, 40.6 % of the patients took at least one diabetes medication, and 35.8 % of the patients with T2DM needed insulin therapy." (PMID 40740163, 2025). "Specifically, the use of previous insulin pump was significantly higher (87%) in MM780G-group and lower (59%) in CAM-APS group and DLBG system users had significantly longer duration of diabetes than the other groups." (PMID 40666106, 2025). "The levels of FBG, INS, and OGTT are key evaluation indicators for the diagnosis and treatment of diabetes patients, reflecting the control of the body’s basic blood sugar levels." (PMID 40941124, 2025). "T2DM was more severe in RYGB patients, with longer diabetes duration (6.1 ± 7.1 vs. 3.1 ± 4.7 years; median 4.0 years [IQR 1.0–9.0] vs. 1.0 years [IQR 0.1–3.0], p < 0.001) and higher insulin use (33.6% vs. 7.2%, p < 0.001)." (PMID 41231326, 2025).